LPAL2 (lipoprotein(a) like 2 (pseudogene) )
Synonyms: APOAL; APOARGC; apo(a)rg-C
Gene: Long non-coding RNA gene on chromosome 6 (160,466,555 to 160,520,306, reverse strand). Ensembl gene ENSG00000290613.
Diseases named in the same sentence as LPAL2 in open-access papers:
LPAL2 is named in the same sentence as 8 diseases in open-access papers, as found by Europe PMC text mining. Sharing a sentence is not in itself a finding about the gene and the disease. The quoted sentences say what the papers report.
glioma (2 papers, 2019 to 2022). A benign or malignant brain and spinal cord tumor that arises from glial cells (astrocytes, oligodendrocytes, ependymal cells). "Six pseudogenes (SP3P, ANXA2P3, PTTG3P, LPAL2, CLCA3P, and TDH) were reported to be associated with overall survival in glioma." (PMID 36333286, 2022). "A prior report that constructed another signature with six pseudogenes (SP3P, ANXA2P3, PTTG3P, LPAL2, CLCA3P, and TDH) for prediction of glioma patient survival." (PMID 31681595, 2019).
hepatocellular carcinoma (2 papers, 2022 to 2026). A malignant tumor that arises from hepatocytes. "Considering the inhibitory role of LPAL2 in the regulation of hepatocellular carcinoma stemness, this pseudogene-derived lncRNA can form the basis of a therapeutic strategy to target the CSC population." (PMID 41431719, 2026). "Here, we found that knockdown of LPAL2 in hepatoma cells impaired doxorubicin-induced cell death by modulating the expression of apoptosis-related markers." (PMID 36010685, 2022). "This analysis showed that LPAL2 expression was decreased in the doxorubicin-resistant hepatoma cell line, MHCC97L-Dox-R." (PMID 36010685, 2022). "The knockdown of LPAL2 in hepatoma cells induced tumor formation, migration, invasion, sphere formation, and drug resistance." (PMID 36010685, 2022). "Besides, a distinct group of hepatocellular carcinoma patients with high expression of LPAL2 and low expression of MMP9 showed a better survival rate." (PMID 41431719, 2026). "Notably, LPAL2 expression was decreased in CD133-negative hepatoma cells, suggesting the involvement of LPAL2 in cancer stem cell-related functions." (PMID 36010685, 2022). "To address this question, we first assessed endogenous LPAL2 expression in hepatoma cell lines." (PMID 36010685, 2022). "To date, the exact functional roles of LPAL2 in hepatoma remain unclear." (PMID 36010685, 2022). "In the current study, we found that the pseudogene-derived lncRNA LPAL2 is downregulated in hepatocellular carcinoma (HCC) tissues, and further showed that elevated LPAL2 expression is positively correlated with survival outcome." (PMID 36010685, 2022). "To verify this, we evaluated LPAL2 expression in hepatoma cell lines treated with or without doxorubicin, and found that LPAL2 expression was repressed by doxorubicin treatment in HA22T and Huh7 cell lines." (PMID 36010685, 2022).
cholangiocarcinoma (1 paper, 2018). A carcinoma that arises from the intrahepatic biliary tree (intrahepatic cholangiocarcinoma) or from the junction, or adjacent to the junction, of the right and left hepatic ducts (hilar cholangiocarcinoma). "Diagnostic value of lncRNAs for Cholangiocarcinoma: HULC(b), H19(c), LPAL2(d), C3P1(e), AC005550.3(f), APOC1P1(g), PVT1(h),and sensitivity: Sen." (PMID 30305026, 2018).
cancer (3 papers, 2021 to 2022). A tumor composed of atypical neoplastic, often pleomorphic cells that invade other tissues. "Collectively, these findings reveal that LPAL2 functions as a suppressor that represses stemness through the modulation of cancer stem cell marker expression." (PMID 36010685, 2022). "LPAL2 was identified as a pseudogene-derived lncRNA, but its functional role in cancer progression is limited." (PMID 36010685, 2022). "Notably, LPAL2 knockdown accelerated sphere formation, indicating that LPAL2 is involved in the cancer stem cell phenotype." (PMID 36010685, 2022). "Moreover, the cancer stem cell-related markers, Nanog, SOX2 and LIN28A, were induced by the depletion of LPAL2." (PMID 36010685, 2022). "Other cancer-related genes are ADAMTS17, LINC01748, LPAL2, SRP14-AS1 and WASH8P." (PMID 33672117, 2021).
tumor (3 papers, 2018 to 2024). "In our study, we established a novel role of LPAL2 in regulating tumor growth, metastasis, sphere formation, and drug resistance." (PMID 36010685, 2022). "Functionally, the knockdown of LPAL2 induces tumor growth, sphere formation, migration, and invasion." (PMID 36010685, 2022). "Specifically, we showed that the knockdown of LPAL2 accelerates tumor growth and metastasis, and that MMP9 is directly regulated by LPAL2." (PMID 36010685, 2022). "To determine how LPAL2 regulates tumor growth, cell migration, invasion and metastasis, we identified LPAL2-regulated target genes through microarray profiling analysis." (PMID 36010685, 2022). "The depletion of LPAL2 induced an increase in tumor growth and tumor weight." (PMID 36010685, 2022). "Taken together, these findings support the conclusion that LPAL2 is a tumor suppressor in HCC." (PMID 36010685, 2022). "In conclusion, our findings advance the novel concept that LPAL2 is a tumor suppressor in HCC." (PMID 36010685, 2022). "Our collective results indicate that LPAL2 acts as a tumor-suppressor lncRNA in HCC." (PMID 36010685, 2022). "In this study, we found that LPAL2 acts as a tumor suppressor lncRNA in HCC cell lines." (PMID 36010685, 2022). "Collectively, our findings establish LPAL2 as a novel tumor suppressor in HCC, and suggest targeting LPAL2 and MMP9 as a therapeutic approach for the treatment of HCC." (PMID 36010685, 2022). "In vitro and in vivo models support the conclusion that LPAL2 modulates tumor growth, metastasis and stemness phenotypes of HCC cell lines, and microarray profiling analysis and validation results suggest that LPAL2 regulates metalloproteinase-9 (MMP9) at the transcriptional level." (PMID 36010685, 2022).
LPAL2 also shares sentences with these, for which no sentence is quoted: cardiovascular diseases (1 paper); coronary artery disease (1); coronary stenosis (1).